C2orf69 (chromosome 2 open reading frame 69)
Description:
May play a role in the respiratory chain.
Synonyms: FLJ38973; COXPD53
Tractability: PROTAC: ubiquitination databases record sites on it; its protein half-life has been measured.
Gene: Protein-coding gene on chromosome 2 (199,911,293 to 199,955,935, forward strand). Ensembl gene ENSG00000178074.
Subcellular location: Mitochondrion matrix
Gene Ontology:
Biological process: oxidative phosphorylation
Cellular component: mitochondrial matrix; mitochondrion
Genetic constraint (gnomAD): Loss-of-function variants: 17 observed, 27.88 expected, observed/expected ratio (o/e) 0.61, 90% interval 0.42 to 0.91. The upper end of that interval is the gene's LOEUF score, 0.91, which puts it in group 3 of 6, group 1 being the genes least tolerant of losing a copy. Missense variants: 401 observed, 476.16 expected, observed/expected ratio (o/e) 0.84, 90% interval 0.77 to 0.92. Synonymous variants: 193 observed, 180.59 expected, observed/expected ratio (o/e) 1.07, 90% interval 0.95 to 1.2.
Homologues: Orthologues: chimpanzee C2orf69 (100% identical), macaque C12H2orf69 (98% identical), rabbit C2orf69 (90% identical), pig C2orf69 (88% identical), dog C2orf69 (86% identical), guinea pig C2orf69 (78% identical), mouse 1700066M21Rik (75% identical), rat C9h2orf69 (75% identical), tropical clawed frog c9h2orf69 (48% identical), zebrafish C9H2orf69 (36% identical), Drosophila melanogaster CG31122 (29% identical).
Diseases named in the same sentence as C2orf69 in open-access papers:
C2orf69 is named in the same sentence as 2 diseases in open-access papers, as found by Europe PMC text mining. Sharing a sentence is not in itself a finding about the gene and the disease. The quoted sentences say what the papers report.
neurodevelopmental disorder (1 paper, 2022). A behavioral and cognitive disorder with onset during the developmental period that involves impaired or aberrant development of intellectual, motor, or social functions. "The team in Iraq was able to obtain exome testing in Germany that revealed a homozygous likely pathogenic variant in the C2orf69 gene, consistent with a genetic diagnosis of the autosomal-recessive C2orf69-related neurodevelopmental-disorder." (PMID 36313873, 2022).
C2orf69 also shares sentences with these, for which no sentence is quoted: autoinflammatory syndrome (1 paper).